CD163 (CD163 molecule)
Diseases named in the same sentence as CD163 in open-access papers (continued):
Sharing a sentence is not in itself a finding about the gene and the disease.
Hernia (2 papers, 2023 to 2025). "Macrophage infiltration (CD68, CD192, CD163), MC classification on MRI, and hernia parameters were analyzed." (PMID 40248336, 2025). "Furthermore, quantification of the M1 (CD86) and M2 (CD163) macrophage subsets indicate a predominance of M1 macrophages within the hernia, with no statistical difference in the M2/M1 ratio between the groups L6w and Mac6w." (PMID 37429889, 2023).
histiocytic neoplasm (2 papers, 2023 to 2024). Histiocytic tumors are a heterogeneous group of tumors and tumorlike masses commonly associated with histologically identical extracranial lesions. "RDD is characterized by excessive tissue infiltration by dendritic cells, macrophages, or monocyte-derived cells, with a histopathologic diagnosis based on the presence of CD68+, CD163+, and S100+ histiocytes, which differentiate it from other histiocytic neoplasms." (PMID 37378192, 2023).
Hydrocephalus (2 papers, 2018 to 2025). Hydrocephalus is an active distension of the ventricular system of the brain resulting from inadequate passage of CSF from its point of production within the cerebral ventricles to its point of absorption into the systemic circulation. "Moreover, the SAH rats with hydrocephalus had higher CD163 immunoreactivity." (PMID 29867324, 2018). "Furthermore, CD163 protein levels were increased in rats with higher SAH grades, the presence of T2 lesions on MRI, or hydrocephalus." (PMID 29867324, 2018).
hypopharyngeal carcinoma (2 papers, 2024 to 2026). Carcinoma, predominantly squamous cell, arising from the epithelial cells of the hypopharynx. "In a tissue microarray cohort of 96 patients, CD68 + and CD163 + macrophages were more abundant in oral and oropharyngeal tumors compared to laryngeal and hypopharyngeal carcinomas (p = 0.001 and p = 0.06, respectively)." (PMID 41591510, 2026). "Again, hypopharyngeal cancers had the lowest number of infiltrating CD68+ and CD163+ macrophages in each compartment (CD68: p < 0.05 vs. oral cavity and CD163: p < 0.05 vs. larynx)." (PMID 39630300, 2024).
intracranial aneurysm (2 papers, 2021 to 2025). "Consequently, immunohistochemical analysis of intracranial aneurysm dome resections have revealed that ruptured intracranial aneurysms from patients possess increased M1 (HLA-DR+) cells opposed to M2 (CD163+) cells." (PMID 33763073, 2021). "Numbers of positively stained saccular intracranial aneurysm (sIA) samples and mean, median, and range of leukocyte densities in CD3+, CD4+, CD8+, CD20+, CD68+, and CD163+ stainings." (PMID 40498464, 2025).
intracranial haemorrhage (2 papers, 2017 to 2021). "Recently, two groups have demonstrated upregulation of neuronal CD163 expression after intracranial haemorrhage in nonhuman models —if this finding is confirmed in humans, neurons in Hp1 individuals may accumulate more intracellular heme/iron, which is toxic." (PMID 29104730, 2017).
invasive carcinoma (2 papers, 2018 to 2022). A carcinoma that is not confined to the epithelium, and has spread to the surrounding stroma. "To investigate the extent to which bone marrow-derived cells contribute to macrophage development in human tissues, we performed CD163-immunoFISH analysis on tumor and non-tumor tissue specimens from three cases of invasive carcinoma (cases 1–3)." (PMID 30272010, 2018). "To investigate the extent to which bone marrow-derived macrophages were present in human tumor or non-tumor tissues, we performed a chimerism analysis of CD163(+) cells in three cases of invasive carcinoma that developed 3.6–19.8 years after bone marrow transplantation." (PMID 30272010, 2018).
iron overload (2 papers, 2018). "Of these only 3 genes (CD163, ADAM17, and TMED7) were significantly linked to systemic iron-overload based on multivariate projection model analyses." (PMID 29980709, 2018). "Livers of patients with iron-overload, showed significantly increased levels of CD163 and ADAM17, correlating with the increase in sCD163 and TNF-α levels." (PMID 29980709, 2018). "Thus, the role of CD163 in hemoglobin uptake, inflammation, early brain injury and iron overload, as well as long-term neurologic deficits deserves further study." (PMID 29867324, 2018).
ischemic cardiomyopathies (2 papers, 2021 to 2025). "However, as it was shown that the majority of heart resident human CD68+ macrophages co-express CD14 in dilated and ischemic cardiomyopathies, we applied CD86 and CD163 as additional markers for M1 and M2 macrophages, respectively." (PMID 33432417, 2021).
kidney failure (2 papers, 2017 to 2025). An acute or chronic condition that is characterized by the inability of the kidneys to adequately filter the blood. "CD163 infiltration correlates with renal severity at diagnosis, which supports the hypothesis that kidney failure might by partially controlled by the recruitment of CD163 positive cells (encompassing dendritic cells and monocytes, which co-express this receptor)." (PMID 40052170, 2025).
laryngeal carcinoma (2 papers, 2022 to 2023). Carcinoma that arises from the laryngeal epithelium. "This is also the first laryngeal study that uses CD163 to pinpoint TAMs in laryngeal cancer." (PMID 37082492, 2023).
liposarcoma (2 papers, 2023 to 2024). A usually painless malignant tumor that arises from adipose tissue. "Other studies revealed that CD14+, CD68+, and CD163+ macrophages were associated with a poor OS in myxoid liposarcoma and dedifferentiated liposarcoma." (PMID 37958467, 2023). "In a study of 134 adults with high-grade LMS, liposarcomas, and SS, a high number of CD163+ TAMs was identified in 49% of all cases and were correlated with the tumor grade in 53% of high-grade and 28% of low-grade tumors." (PMID 37958467, 2023). "In dedifferentiated liposarcoma and LMS, a high infiltration of CD163+ TAMs was a prognostic factor with a longer PFS." (PMID 37958467, 2023).
liver failure (2 papers, 2014). A liver disease characterized by the liver losing or has lost all of its function. "Clinical evidence from liver-failure patients suggests a close association between the level of CD163 expression in serum and a fatal disease outcome." (PMID 24597777, 2014). "Consistent with our results, other investigators have reported the up-regulation of CD163 in patients with liver failure." (PMID 24597777, 2014). "Consistent with a role in the late inflammatory response, the expression of CD163 is up-regulated in patients with liver failure." (PMID 24597777, 2014). "Increased expression of CD163 (known to be involved in several anti-inflammatory functions of the immune system) in patients with liver failure is significantly correlated with a fatal outcome." (PMID 24597777, 2014). "However, the high levels of CD163 in liver failure may represent an anti-inflammatory imbalance, especially in patients with poor disease outcomes." (PMID 24597777, 2014).
Lymphatic Metastasis (2 papers, 2022 to 2025). Transfer of a neoplasm from its primary site to lymph nodes or to distant parts of the body by way of the lymphatic system. "FOXP3 (p = 0.0017) and CD163 (p = 0.0316) expression levels were significantly higher in the Hematogenous Metastasis compared to both the Primary Tumor and Lymphatic Metastasis." (PMID 41179298, 2025).
malignant thyroid neoplasms (2 papers, 2023 to 2025). "The number of immune cells in cytological specimens correlated with CD8+ (r = 0.693; p < 0.001) and CD163+ cells (r = 0.559; p < 0.001) in histological samples, reflecting the differences in the tumor immune microenvironment between benign and malignant thyroid neoplasms." (PMID 39936166, 2025). "In thyroid cancer, Angell and colleagues demonstrated that there was a tendency for BRAF mutant tumors to have higher CD163 expression than CD80, but they also reported that this varied significantly between patients, with some having higher CD80 and others CD163." (PMID 37686663, 2023).
metastatic prostate carcinoma (2 papers, 2017 to 2025). A carcinoma that arises from the prostate gland and has spread to other anatomic sites. "The findings of this study emphasize FOXP3, CD163, and PD-1 as key indicators of immune modulation across primary and metastatic prostate cancer." (PMID 41179298, 2025). "CD163 staining was performed on the primary tumor, a negative draining lymph node, and a level four lymph node with a focus of metastatic prostate cancer and compared to benign controls." (PMID 28716144, 2017).
microcephaly (2 papers, 2018 to 2019). A congenital or acquired developmental disorder in which the circumference of the head is smaller than normal for the person's age and sex. "In cases of microcephaly, the expression of CD163 is important because in flaviviruses, the scavenger receptor CD163 is one of the receptors used by these viruses to enter the cell." (PMID 29311619, 2018). "Brain slices of a ZIKV-positive human fetus (5 months) diagnosed with microcephaly were stained for the viral protein NS1 together with the leukocyte marker CD45, the monocytic marker CD14, or the myeloid markers CD68 or CD163." (PMID 31562326, 2019).
microhematuria (2 papers, 2020 to 2025). "The renal tissues of six patients with microscopic hematuria but normal histology were stained with anti-CD68 and anti-CD163." (PMID 32034190, 2020).
migraine (2 papers, 2023 to 2025). "Although several markers, such as CD11β, CD68 and CD163 and iNOS have been used in migraine and neuroinflammation studies to identify functionally distinct microglial subsets, we selected Iba-1 as the sole microglial marker for this study." (PMID 41515906, 2025).
myelofibrosis (2 papers, 2021 to 2025). A partial or complete replacement of the bone marrow stroma by fibrous tissue. "ROC curve analyses demonstrated that the CD68/CD163 ratio provided the best diagnostic accuracy for both thrombosis and secondary myelofibrosis, outperforming individual markers." (PMID 41239536, 2025). "A CD68/CD163 ratio > 1.63 was significantly associated with shorter TFFS and secondary myelofibrosis PFS." (PMID 41239536, 2025). "Using a cut-off of 1.63, the CD68/CD163 ratio yielded a sensitivity of 66.7% and specificity of 63.3% for thrombosis prediction (AUC = 0.677), and for secondary myelofibrosis, a cut-off of 1.55 gave a sensitivity of 80.9% and specificity of 75% (AUC = 0.779)." (PMID 41239536, 2025). "Prospective clinical cohorts will need to determine a correlative or predictive value of CD163 or CD68 as a parameter accompanying or predicting myelofibrosis." (PMID 33104881, 2021).
Opportunistic infection (2 papers, 2014 to 2022). An infection that is caused by a pathogen that would generally not be able to cause an infection in a host with a normal immune system. "The shift in CD68− and CD68+CD163− macrophages to a CD163 phenotype has functional implications in their ability to defend against opportunistic infections, since these cells serve as antigen-presenting cells that are required for mounting effective adaptive immune responses." (PMID 35203323, 2022). "Monocytes with high CD163 expression show an impaired ability to present antigens and produce TNF-α, and may represent a possible defect that is directly linked to the development of recurrent bacterial and opportunistic infections." (PMID 24597777, 2014).
penile cancer (2 papers, 2021 to 2022). A primary or metastatic malignant neoplasm that affects the penis. "A high level of CD163+ TAMs (M2) was found to be associated with worse prognosis and higher tumor stage in NSCLC, whereas in penile cancer, a high level of CD163+ TAMs was associated with increased LNM rather than poor survival." (PMID 36524123, 2022).
renal failure (2 papers, 2017 to 2022). "Baseline severity of renal insufficiency (p = 0.02), urine soluble CD163 (usCD163) (p = 0.002) and “sclerotic” Berden histological class (p = 0.001) were key determinants of ESKD risk." (PMID 37251362, 2022).
rosacea (2 papers, 2021 to 2024). A chronic erythematous skin disorder that affects the face. "The number of CD163-positive cells was reported to be higher in the rosacea subtypes erythematotelangiectatic, papulopustular, and phymatous rosacea than in healthy skin, and CD163 expression was highest in papulopustular rosacea." (PMID 33800730, 2021). "The CD163 expressed in macrophages play a key role in the etiology of rosacea." (PMID 33800730, 2021). "Therefore, CD163+ macrophages may contribute to the development of AS in rosacea and acne patients." (PMID 38321132, 2024).
Rosai-Dorfman disease (2 papers, 2025). "Rosai-Dorfman disease histiocytes are typically positive for CD68, CD163, and S100, while negative for CD1a and langerin." (PMID 40398847, 2025).
Salmonella Infections (2 papers, 2018 to 2025). Infections with bacteria of the genus SALMONELLA. "In mouse peritoneal MΦs, Salmonella infection up-regulated the expression of both of M1 MΦ markers (CCR7 and CD86), M2 MΦ marker (CD163 and CD206) and induced the secretion of M1 MΦ marker TNF-α and M2 MΦ marker IL-10 in ascitic fluid significantly." (PMID 30271755, 2018).
sarcopenia (2 papers, 2022 to 2024). Progressive decline in muscle mass due to aging which results in decreased functional capacity of muscles. "Our study investigated the plasma proteome of individuals with age-related sarcopenia and identified 8 DEPs that showed promising predictive performance, including IGFBP2, PON3, LRG1, PRDX6, PTGDS, CD163, PRG4, and TRAJ17." (PMID 39725826, 2024).
sickle cell disease (2 papers, 2024). Sickle cell anemias are chronic hemolytic diseases that may induce three types of acute accidents: severe anemia, severe bacterial infections, and ischemic vasoocclusive accidents (VOA) caused by sickle-shaped red blood cells obstructing small blood vessels and capillaries. "CD163 prevented hepatobiliary injury in sickle cell disease by means of inhibiting oxidative stress, inflammation, and thrombosis; and the reducing PEX14 impaired peroxisomes and caused liver oxidative stress." (PMID 39598613, 2024).
soft tissue tumors (2 papers, 2023 to 2025). "SSs, like other soft tissue tumors, exhibit heterogeneous immune infiltrates, with CD163+ macrophages and regulatory T cells contributing to an immunosuppressive condition." (PMID 40423041, 2025). "Our results are in accordance with studies performed in soft tissue tumors such as HNSCC, in which CD163+ TAMs correlate with poorer patient survival." (PMID 36831348, 2023).
thalassemia (2 papers, 2018 to 2022). An inherited blood disorder characterized by a decreased synthesis of one of the polypeptide chains that form hemoglobin. "Our data showed that VCAM-1, VEGF and CD163 are elevated in all patient groups, thus representing markers associated to thalassemia, independently from severity of the disease." (PMID 36699704, 2022). "Expression of ADAM17 and CD163 was increased (p < 0.05) in the hepatic tissue (cytoplasmic) and macrophages (sinusoidal spaces) in thalassemia patient’s liver tissue." (PMID 29980709, 2018). "In thalassemia patients we also observed a significant positive correlation between ferritin levels and CD163 concentrations (p < 0.05) and a negative correlation between LIC values and ang-1 (p < 0.05)." (PMID 36699704, 2022).
Thyroid carcinomas (2 papers, 2023 to 2025). "Tumor-associated macrophages (TAMs), including both M1 (CD68+) and M2-type (CD163+), were shown to be the most numerous immune cells infiltrating thyroid carcinoma." (PMID 39936166, 2025).
thyroid tumor (2 papers, 2019 to 2025). A benign or malignant neoplasm affecting the thyroid gland. "TAMs in thyroid tumors display an M2 phenotype (i.e. express CD163 and interleukin 10), and are likely to promote tumor progression and/or inhibit tumor elimination." (PMID 31113465, 2019). "When applying dichotomic assessment of immune cell numbers as low or high in thyroid tumors, we found that most TA demonstrated a low number of CD8+, CD68+ and CD163 cells." (PMID 39936166, 2025).
tongue leukoplakia (2 papers, 2019 to 2024). "In tongue leukoplakia, CD163+ macrophages infiltration correlates with immunosuppressive cytokine IL‐10 expression." (PMID 31890299, 2019).
urothelial carcinoma (2 papers, 2023 to 2025). A malignant neoplasm derived from the transitional epithelium of the urinary tract (urinary bladder, ureter, urethra, or renal pelvis). "Finally, digital spatial profiling of sarcomatoid urothelial carcinoma reveals an immunosuppressive microenvironment with CD163‐positive cells, implicating them in EMT and aggressive phenotype." (PMID 40891689, 2025).
Waldenstrom macroglobulinemia (2 papers, 2024 to 2025). "CD163 is a well-recognized marker for M2-polarized macrophages, but CD163 is also the marker for MDSCs in Waldenstrom’s macroglobulinemia." (PMID 38786019, 2024).
Acute cholecystitis (1 paper, 2026). "Acute cholecystitis showed epithelial disruption, edema, and dense infiltration by neutrophils and macrophages, including an increased density of CD163+ macrophages, accompanied by elevated systemic inflammation." (PMID 41781757, 2026).
adenomyosis (1 paper, 2025). The growth of endometrial tissue inside the muscular wall of the uterine corpus. "Compared to women without adenomyosis, the density of CD163+ M2 macrophages in the eutopic endometrium of patients with severe diffuse or local adenomyosis is significantly increased." (PMID 39966111, 2025).
Adrenal insufficiency (1 paper, 2018). Insufficient production of steroid hormones (primarily cortisol) by the adrenal glands. "Decreased serum levels of sCD163, especially in cases of thyroid dysfunction or adrenal insufficiency, indicates that CD163+ macrophages have been activated and effector cells have been recruited to the target organ, both of which underly the development of irAEs by nivolumab." (PMID 29643991, 2018).
androgen excess (1 paper, 2013). "In a study on women with hyperinsulinemic androgen excess, OCT lead to an increase in CD163 gene expression contrary to our findings in a hypogonadal model." (PMID 24148221, 2013).
angioimmunoblastic T-cell lymphoma (1 paper, 2013). A mature T-cell non-Hodgkin lymphoma, characterized by systemic disease and a polymorphous infiltrate involving lymph nodes and extranodal sites. "CD163 is also a marker of macrophages, and previous reports revealed that the number of CD163-positive macrophages reflects prognosis in angioimmunoblastic T-cell lymphoma (AITL)." (PMID 24236041, 2013).
ankylosing spondylitis (1 paper, 2013). An autoimmune chronic inflammatory disorder characterized by inflammation in the vertebral joints of the spine and sacroiliac joints. "Consistent with this is the demonstration that CD163-positive macrophages infiltrating the fibrous tissue in facet joints of patients with ankylosing spondylitis are a major source of inflammatory cytokines, such IL-23." (PMID 23922818, 2013).
arterial disease (1 paper, 2023). "Soluble CD163 was 1.3-fold (p = 0.015) higher in AAA compared to patients without arterial disease." (PMID 37107322, 2023).
Ascites (1 paper, 2019). Accumulation of fluid in the peritoneal cavity (between the layers of the peritoneum that lines the abdomen). "As previously reported, CD163 and CD206 are surface markers on TAMs in HGSC ascites associated with protumorigenic functions and a poor clinical outcome." (PMID 30353652, 2019).
astrocytic tumor (1 paper, 2015). A glial tumor of the brain or spinal cord showing astrocytic differentiation. "In original tumor material, with double immunofluorescence we confirmed that receptor expression occurred in GFAP-positive astrocytic tumor cells as well as on CD68/CD163-positive microglia/macrophages." (PMID 25894595, 2015).